Y_RNA (Y RNA )
Gene: Miscellaneous RNA gene on chromosome 3 (130,914,340 to 130,914,452, reverse strand). Ensembl gene ENSG00000252894.
Homologues: Orthologues: chimpanzee Y_RNA (100% identical), macaque Y_RNA (96% identical). Paralogues in human: Y_RNA (84% identical), Y_RNA (82% identical), RNY1P1 (81% identical), Y_RNA (81% identical), RNY1P5 (81% identical), Y_RNA (80% identical), RNY1P3 (79% identical), Y_RNA (79% identical), RNY1P11 (78% identical), Y_RNA (78% identical), RNY1 (77% identical), Y_RNA (77% identical), and 91 more.